GLUD1 (glutamate dehydrogenase 1)
Diseases named in the same sentence as GLUD1 in open-access papers (continued):
Sharing a sentence is not in itself a finding about the gene and the disease.
tumor (continued). "The glutamine dehydrogenase activity is needed for tumor cell survival during glycolysis impairment and an altered expression of GLUD1 may affect cell proliferation, migration, and invasion." (PMID 35008989, 2022). "In ccRCC, GLUD1 level was downregulated and acted as tumor suppressor and might be a therapeutic target for ccRCC." (PMID 36203437, 2022). "To detect whether SIRT4 plays a tumor-suppressive role through the modification of GLUD1 in PCa, we performed various rescue experiments." (PMID 35847357, 2022). "Particularly in GBM, the accumulation of Glu due to GPT2 and GLUD1 downregulation correlated to upregulation of genes related to GSH synthesis which could favor tumor cell survival, mostly in the most aggressive MS subtype." (PMID 33910646, 2021). "Moreover, several pivotal enzymes involved in amino acid metabolism process and urea cycle were identified with decreased lysine acetylation levels in HCC tumor tissues, such as GLUD1, ASL, GOT2 and so on." (PMID 33093847, 2020). "In addition, glutamate dehydrogenase 1- (GDH1-) produced α-KG directly binds to and activates I-kappaB kinase beta (IKKβ) and NF-κB signaling, which promotes glucose uptake and tumor cell survival by upregulating glucose transporter 1 (GLUT-1)." (PMID 32461965, 2020). "High GLUD1 expression or low SLC25A13 expression was found to be associated with tumor aggressiveness, including depth of tumor invasion, lymph node and distant metastasis, lymphatic and venous invasion, and stage." (PMID 27924922, 2016). "In particular, this included genes involved in secretory pathways, lipid and sugar metabolism (such as, UGDH, SORD, GLUD1, ELOVL5, ASCL3, UAP1), but also genes implicated in tumor progression and metastasis with functions in cell survival, proliferation and adhesion (EHF, ELL2, TPD52, MAFB, SGK)." (PMID 21829708, 2011). "However, supplementation of 2‐OG (a downstream metabolite of GLUD1) did not affect tumor antigen presentation under glutamine deficiency." (PMID 39482885, 2025). "Additionally, we investigated the influence of GLUD1 on HCC tumor growth in vivo." (PMID 38216781, 2024). "It suggested that GLUD1 might function as a tumor suppressor during the progression of HCC." (PMID 38216781, 2024). "Moreover, GLUD1 inhibited the protein expression of IL-32 in HCC tumor xenografts." (PMID 38587834, 2024). "We then explored GLUD1 expression in ccRCC separately in the UALCAN, and it was clear that GLUD1 mRNA and protein expression showed a decreasing trend in tumor tissues, and these results suggest that GLUD1 may be a suppressor factor in most tumors, including ccRCC." (PMID 38245763, 2024). "However, it should be noted that the expression of GLUD1 in different neoplasms is diverse." (PMID 38587834, 2024). "The correlation between SLC1A5 and GLUD1, which is involved in the conversion of Gln to alpha-ketoglutarate for the TCA cycle and subsequent gluconeogenesis, in luminal A tumours suggests that Gln is utilised for this process." (PMID 39843491, 2025). "GLUD1, downregulated in HCC, activates the JNK/p38 MAPK pathway through enhanced ROS production and mitochondrial respiration, suppressing tumor progression—a process reversible by ROS scavengers." (PMID 41502527, 2025). "Altogether, these observations suggest that the reduced expression of GLUD1 is relevant to HCC development and poor tumor prognosis." (PMID 38587834, 2024). "In PCa models, SIRT4’s inhibition of glutamate dehydrogenase 1 (GDH1), a key enzyme in glutamine metabolism, was observed to curb metabolic pathways essential for tumor proliferation." (PMID 39796040, 2024). "GLUD1 silencing enhanced HCC cell growth and migration in vitro and the growth of HCC tumor xenografts in vivo." (PMID 38587834, 2024). "The authors suggested that the downregulation of GLUD1 in GBM increased the source of glutamate for glutathione synthesis and enhanced tumor cell fitness due to increased antioxidative capacity." (PMID 37100462, 2023).
tumor (continued). "In addition, a recent study reported that GLUD1 could regulate redox homeostasis and tumor growth." (PMID 35847357, 2022). "On the other hand, LF tumours displayed suppressed expression of GLS and GLUD1, referring a decreased glutaminolysis to enter into TCA cycle for mitochondria oxidative bioenergetics." (PMID 36615660, 2022). "Glutamate is physiologically important to tumor cells 38; thus, we constructed LUAD cell-based Dox-inducible GGG cells in which GLUD1 overexpression (G) and GLAST (G) and GLT1 knockdown (G) was simultaneously achieved." (PMID 33897873, 2021). "With respect to the luminal subtypes, both luminal A (low proliferative) and B (high proliferative) tumours showed a weak positive correlation between GLS mRNA and protein expression with GLUD1 and SLC38A2 (p < 0.01)." (PMID 34439127, 2021). "Craze and colleagues have shown that there is a relationship between GLUD1 and luminal tumours compared to HER2+ tumours." (PMID 34439127, 2021). "Most of these genes are enzymes in the metabolism of tumor cells, such as HS3ST3B1, GLUD1, BCAT1, and ACAA2." (PMID 32280672, 2020). "GLUD1 plays an important role in glutamine consumption, which is a common feature of HCC liver tissues and provides energy for tumor growth." (PMID 33093847, 2020). "Several of the understudied genes are directly involved in critical metabolic pathways of tumor etiology, including glucose metabolism (SORD), lipid biosynthesis (FAR1), cAMP signaling pathway (PDE7A, ADCY6), and glutamate anaplerosis (ABAT, GLUD1)." (PMID 31231467, 2019). "Immunostaining of histological sections also showed that resibufogenin stimulated the expression of RIP3, PYGL, GLUD1 and GLUL in the tumor tissues." (PMID 30029665, 2018). "These in vivo data suggested that resibufogenin inhibits tumor growth through inducing RIP3-mediated activation of PYGL, GLUD1 and GLUL to induce necroptosis in CRC cells." (PMID 30029665, 2018). "Glutamate can then be metabolized either to GSH by GCLC or to 2‐OG by GLUD1 and then enter the TCA cycle.[10b] To find out which metabolic pathway(s) downstream of GLS plays a primary role in regulating tumor antigen presentation, we performed in silico metabolic flux analysis using TCGA datasets." (PMID 39482885, 2025). "Using a Mitochondria/Cytosol Protein Isolation Kit, followed by western blot analysis, GLUD1 and AKT proteins were detected in both the mitochondria and cytosol of HCC cells, suggesting that GLUD1 interacts with AKT and affects AKT activation directly in these regions of tumor cells." (PMID 38587834, 2024). "In most of the tumors, the methylation of GLUD1 was significantly elevated in tumor tissues compared to normal tissues." (PMID 38245763, 2024). "Consistent with previous observations, overexpression of GLUD1 suppressed HBX-facilitated cell growth and migration in HBX-expressing HCC cells and the growth of HCC tumor xenografts induced by HBX in vivo." (PMID 38587834, 2024). "In addition, some SNO proteins can participate in the proliferation, metastasis, and apoptosis of CRC by regulating the tumor endocrine and metabolic pathways, such as PKM, GAPDH, LDHA, GLUD1, and PTGES3." (PMID 37124724, 2023). "Western blotting confirmed the overexpression of SIRT5 WT and SIRT5 H158Y in the xenograft tumor lysates, and we did not observe a significant change in GLUD1 protein level." (PMID 29416026, 2018). "The canonical type refers to a phenotype in which tumors rely on glutamate dehydrogenase (GLUD1) for glutamine utilization; whereas non-canonical type refers to a phenotype in which tumor rely on aspartate transaminase (GOT1) for glutamine utilization." (PMID 25719198, 2015). "Additionally, KRAS G12D mutation regulates the transcription of key metabolic enzymes such as glutamate dehydrogenase (GLUD1) and aspartate aminotransferase (GOT1), enabling tumor cells to meet carbon and nitrogen demands for rapid proliferation and macromolecular synthesis." (PMID 40427667, 2025).
tumor (continued). "Moreover, the glutaminolytic enzyme GLUD1 (glutamate dehydrogenase 1) and pyruvate carboxylase, an enzyme interconverting OAA and pyruvate, were clearly expressed in macrophages from normal lung, while their expression was less prominent in tumor macrophages." (PMID 41160607, 2025). "According to the results of Gene Ontology (GO) analysis, several SNO proteins, such as glutamate dehydrogenase 1 (GLUD1), pyruvate kinase PKM (PKM), and prostaglandin E synthase 3 (PTGES3), might be involved in the metabolic pathways that are important in tumor endocrine biological processes." (PMID 37124724, 2023).
infection (4 papers, 2020 to 2025). The state of being infected such as from the introduction of a foreign agent such as serum, vaccine, antigenic substance or organism. "A second wave of transcription induction was observed at 48h post-infection and included Glud1 and Gls involved in the transformation of glutamine to glutamate (glutaminolysis-related enzymes)." (PMID 32214337, 2020). "PoRVA infection induces increased expression levels of SLC1A5, GLS1, and GLUD1, which enhance glutamine uptake, TCA cycle flux, and ATP production." (PMID 38905309, 2024). "During PoRVA infection, the activity and protein expression levels of glutamine catabolism-related enzymes (GLS1 and GLUD1) were also significantly increased promoting ATP production through glutamine anaplerosis into the TCA cycle." (PMID 38905309, 2024). "Here, we observed that PoRVA infection increased the enzymatic activity and expression of GLS1 and GLUD1, which are related to glutamine catabolism, with RVA-HNNY infection having a more pronounced effect than RVA-SXXA infection." (PMID 38905309, 2024). "Notably, RVA-HNNY infection more markedly promoted SLC1A5, GLS1 and GLUD1 expression to more significantly increase the uptake and catabolism of glutamine than RVA-SXXA infection." (PMID 38905309, 2024). "Among these genes, glutaminase 1 (GLS1) and glutamate dehydrogenase 1 (GLUD1) enzyme activity and protein expression were elevated, while glutamic oxaloacetic transaminase (GOT1 and GOT2), glutamate pyruvate transaminase 2 (GPT2), and glutamine synthase (GS) were unchanged during PoRVA infection." (PMID 38905309, 2024).
brain disorder (3 papers, 2019 to 2025). A disease affecting the brain or part of the brain. "Finally, we explore domain-specific therapeutic strategies, including peptide mimetics, synthetic organizers, and non-ionotropic modulators, positioning GluD1 as a promising target for circuit-level intervention in brain disorders." (PMID 41345253, 2025). "Furthermore, five out of the 12 RG‐specific proteins (COL11A1, RRAS, GLUD1, IFITM3, and MGST1) are involved in human epileptic disorders prompting the hypothesis that modification of the extracellular environment is a common feature in this type of brain disease." (PMID 32378798, 2020).
neurodevelopmental disorder (3 papers, 2013 to 2025). A behavioral and cognitive disorder with onset during the developmental period that involves impaired or aberrant development of intellectual, motor, or social functions. "The significant overlap among these clusters strongly positions the GluD1 interactors as a pivotal hub in the pathophysiology of neurodevelopmental disorders." (PMID 41515947, 2025). "The developmental expression pattern and potential role in synapse formation further supports a relationship between GluD1 dysfunction and neurodevelopmental disorders." (PMID 23560106, 2013). "Together, these results highlight an important role for GluD1 in neuronal functions and may provide new insights into the therapeutic strategies for neurodevelopmental disorders." (PMID 41515947, 2025).
neurological disorders (3 papers, 2023 to 2026). "The role of GluD1 is also becoming evident in neurological disorders, particularly chronic pain." (PMID 41636022, 2026). "This suggests a more localized intolerance to variation in this domain of GluD1 M3 compared to GluD2 and demonstrates a new functional mechanism by which GRID1 variants might trigger neurological disease." (PMID 37944084, 2024). "Transgenic animal models provide insight into potential roles of GluD1 in neurological disease." (PMID 37944084, 2024). "Distorted GLUD1 function plays a role in several psychiatric and neurological disorders." (PMID 37100462, 2023).
colorectal (1 paper, 2022). "SIRT5 overexpression is significantly correlated with poor prognosis in CRC, and scientists have found that glutamate dehydrogenase 1 (GLUD1) can be deglutarylated and activated via SIRT5 to promote cellular glutaminolysis, thus enhancing colorectal carcinogenesis." (PMID 35428309, 2022).
neurodegenerative disease (1 paper, 2017). A disorder of the central nervous system characterized by gradual and progressive loss of neural tissue and neurologic function. "In other words, both KA-treated mice and Glud1 Tg mice exhibit excessive neuronal excitation, which has been indicated as a common mechanism underlying aging or neurodegenerative diseases such as AD." (PMID 28057021, 2017).
GLUD1 also shares sentences with these, for which no sentence is quoted: Parkinson disease (4 papers); bipolar disorder (3); epilepsy (3); Ataxia (2); autism (2); autism spectrum disorder (2); clear cell renal cell carcinoma (2); colon cancer (2); diabetes type II (2); schizoaffective disorder (2); acute promyelocytic leukemia (1); alcohol dependence (1); amyloid diseases (1); bacterial infection (1); bladder tumor (1); brain tumors (1); breast tumors (1); cerebellar ataxia (1); Cerebellar atrophy (1); cervical adenocarcinoma (1); Co-infection (1); diffuse midline glioma (1); epileptic seizures (1); fumarase deficiency (1); gout (1); Huntington disease (1); hyperinsulinism-hyperammonemia syndrome (1); hypothyroidism (1); Insulin resistance (1); kidney cancer (1).
A further 14 diseases each share a sentence with GLUD1 in 1 paper.